IL6 (interleukin 6)
Diseases named in the same sentence as IL6 in open-access papers (continued):
Sharing a sentence is not in itself a finding about the gene and the disease.
sarcopenia (continued). "Another study by Yu-Dong Rong investigating IL-6 and IL-10 in 82 elderly Chinese population with sarcopenia found that IL-6 level and IL-6/IL-10 ratio were positively associated with sarcopenia." (PMID 36309772, 2022). "Reduced insulin signaling and increased levels of inflammatory cytokines such as interleukin (IL)-1, IL-6, and tumor necrosis factor-alpha have been suggested to be associated with sarcopenia." (PMID 36143016, 2022). "Serum TNF‐α and IL‐6 are increased in the elderly and associated with sarcopenia and elevated risk for mortality." (PMID 34708577, 2022). "Sarcopenia and schizophrenia share some common mechanisms; interleukin (IL)-6 has been implicated in the pathogenesis of sarcopenia." (PMID 36311511, 2022). "On the other hand, the SASP significantly contributes to sarcopenia via inflammaging, where the persistent levels of IL-6 harm muscle integrity and function, causing muscle degradation and atrophy." (PMID 35954203, 2022). "It was reported inflammatory biomarkers, such as interleukin-6 and hsCRP, are significantly correlated with dialysis-associated sarcopenia." (PMID 35634405, 2022). "Second, chronic low-grade age-related inflammation, characterized by elevated interleukin-6 and tumor necrosis factor-α, for example, has also been reported as an important causal factor for both sarcopenia and lower cognitive performance." (PMID 34161525, 2021). "As blood biomarkers have been shown to be associated with the development of sarcopenia, this study will measure common blood biomarkers of IL-6, TNF-α, CRP, GH, IGF-1, and MSTN and FST as outcome measures." (PMID 34348792, 2021). "There is growing evidence that increasing pro-inflammatory markers such as TNF-α, IL-1β, IL-6 are the main cause of skeletal muscle wasting and sarcopenia." (PMID 34041251, 2021). "Chronic low-grade inflammation caused by IL-6 is a major cause of sarcopenia and part of the aging process." (PMID 34943268, 2021). "Released by macrophages, Interleukin 1 beta (IL-1β) has been, together with TNF-α, one of the most clinically studied cytokines, as well as being also better associated with anorexia, weight loss and sarcopenia than Interleukin 6 (IL-6)." (PMID 33202621, 2020). "Development of sarcopenia has been previously associated with overexpression of pro-inflammatory factors, particularly IL-6, TNF-α, and C-reactive protein." (PMID 33375628, 2020). "Univariate logistic regression analysis highlighted increased IL-6 as a risk factor for sarcopenia, with an increase in plasma IL-6 associating with a slower walking speed in the older adult (n = 854 mean age of 74.3 ± 2.7 years)." (PMID 32517136, 2020). "Inflammation due to increased generation of cytokines such as TNFα, IL-1β and IL-6 has been implicated in the pathogenesis of sarcopenia." (PMID 33260150, 2020). "The findings suggest that 1,25(OH)2D3 can prevent or improve sarcopenia, which is associated with IL-6." (PMID 32899782, 2020). "Sarcopenia and loss of muscle strength have been associated with increased serum concentrations of inflammatory markers, including IL-6, CRP, and TNF-alpha." (PMID 31590379, 2019). "In older patients, the immunoregulatory system is often unbalanced toward a pro-inflammatory state, and the accumulation of proinflammatory cytokines such as IL-6 and TNFα is associated with the development of sarcopenia." (PMID 31248132, 2019). "Increased levels of proinflammatory interleukin 6 have been associated with sarcopenia, low BMI, and the promotion of tumorigenesis and distant metastases." (PMID 31226155, 2019). "Previous observational and review studies showed that sarcopenia is associated with elevated levels of inflammatory cytokine IL-6, IL-6/IL-10, and anti-inflammatory cytokine IL-10." (PMID 31906011, 2019).
sarcopenia (continued). "The ‘frailty syndrome,’ consisting of sarcopenia, anorexia and declining mobility, is associated with dysregulation of pro-inflammatory pathways, increasing inflammatory markers such as IL-6, bone marrow suppression and chronic anemia." (PMID 29752534, 2018). "Following adjustment for potential confounders (age, sex, BMI, physical activity, nutritional risk, VFA), positive associations were present between sarcopenia and IL-6 levels, IL-10 levels, and IL-6/IL-10 ratios." (PMID 30541467, 2018). "Sarcopenia was associated with increased levels of inflammatory cytokine IL-6, anti-inflammatory cytokine IL-10, and IL-6/IL-10 ratios." (PMID 30541467, 2018). "Secondly, the cross-sectional design limits us from identifying a cause-effect association between sarcopenia and IL-6 levels, IL-10 levels and IL-6/IL-10 ratios." (PMID 30541467, 2018). "Age, BMI, levels of physical activity, nutritional risk, VFA, IL-6, IL-10, IL-6/IL-10 ratio were independently associated with the presence of sarcopenia in univariate regression analyses." (PMID 30541467, 2018). "Another study reported that IL-6 mediates sarcopenia in cancer-associated cachexia by activating FOXO3 and atrogin." (PMID 28388585, 2017). "The cytokine IL-6 is a major factor modulating muscle mass and ultimately causing sarcopenia as well as reduction in bone density." (PMID 27465019, 2016). "Certainly, IGF1 has been of particular interest in aging research over the years, and low circulating levels of IGF1, particularly in combination with elevated IL-6, have been associated with decreased muscle strength and increased prevalence of sarcopenia." (PMID 26856410, 2016). "In contrast, suPAR appeared to primarily reflect sarcopenia-associated inflammation, whereas IL-6 was central in both adiposity- and sarcopenia-associated inflammation." (PMID 26244048, 2015). "Associations with sarcopenia have also been demonstrated in the Framingham Heart Study (IL-6) and the Longitudinal Aging Study Amsterdam (IL-6, CRP) and have recently undergone systematic review." (PMID 24472098, 2013). "Several studies have implicated elevated levels of two cytokines, interleukin-6 (IL-6) and TNFα, in the development of sarcopenia." (PMID 21832306, 2011). "Elevated levels of IL-6 have been associated with sarcopenia." (PMID 40151718, 2025). "Since sarcopenia is associated with elevated levels of IL-6, IL-17A, and TNF-α, patients with sarcopenic obesity may face a higher risk of swelling due to this combined inflammatory burden." (PMID 41233862, 2025). "However, in aging populations, chronically elevated IL-6 levels have been strongly associated with the development and progression of sarcopenia, as persistent inflammation disrupts muscle homeostasis, leading to both muscle mass loss and functional decline." (PMID 40944148, 2025). "In preliminary clinical investigations, a single FMT via colonoscopy from healthy young donors in elderly patients with sarcopenia was associated with a reduction in IL-6 and TNF-α levels, along with a significant increase in the abundances of Faecalibacterium, Roseburia, and Prevotella." (PMID 41480113, 2025). "This increase in oxidative stress is associated with a greater risk of sarcopenia, which is inversely related to skeletal muscle mass and correlates with elevated levels of myokines, including proinflammatory interleukin-6 (IL-6) and tumor necrosis factor-α (TNF-α)." (PMID 40243531, 2025). "Furthermore, elevated levels of the inflammatory cytokines, TNF-alpha and IL6, are associated with reduced muscle mass, muscle function and sarcopenia." (PMID 40772803, 2025). "The immune system may be the potential mechanism; IL‐6 was reported to be implicated in the pathogenesis of sarcopenia and the binding of IL‐6 to IL‐6 receptor could initiate gp130‐dependent signaling pathway which would activate ERK1/2." (PMID 38532712, 2024).
sarcopenia (continued). "Prospective clinical investigations have pointed out that elevated serum IL-6 could be associated with sarcopenia in elderly patients with hepatic cirrhosis or chronic pulmonary obstructive disease (COPD)." (PMID 39683624, 2024). "It has been proposed that some inflammatory cytokines, such as IL-6 and IL-10, cause muscle atrophy; High levels of IL-6 are associated with reduced muscle mass and muscle strength, and sarcopenia and sarcopenic obesity have drastically increased C-reactive protein levels." (PMID 37815907, 2024). "MR provide a causal inference approach to establish whether the association between IL-6 or sIL6 and sarcopenia is causal or merely a correlation." (PMID 38750566, 2024). "High levels of the proinflammatory cytokines tumor necrosis factor-α and IL-6 are associated with sarcopenia due to low GS and muscle mass and may exacerbate insulin action." (PMID 39408048, 2024). "Thus, among cytokines linked to aging and inflammaging, which are implicated in sarcopenia and frailty, IL-6 is a critical contributor to PHN." (PMID 38892810, 2024). "IL6 has been linked to loss of muscle mass and poor physical performance in both older adults and PD and a reduction in the number of motoneurons has been observed both in sarcopenia and PD." (PMID 37594550, 2023). "Multivariate logistic regression analysis showed that older age and higher concentrations of pro-inflammatory cytokine levels of IL-6 were significantly associated with a greater risk of sarcopenia, after adjustments for potential known biological and body composition factors." (PMID 37161054, 2023). "In particular, IL-6 was associated with frailty and sarcopenia in people aged 75 years." (PMID 37173873, 2023). "In the multivariate analysis, participants at an older age showed higher concentrations of the blood pro-inflammatory marker of IL-6 and a significantly increased risk of sarcopenia, after taking into consideration other potential factors such as gender and adiposity levels." (PMID 37161054, 2023). "Since several factors were significantly associated with sarcopenia risk in these populations, we stratified the risk by age, body composition indicators of BMI and percentage of body fat and blood IL-6 concentration in both unadjusted simple and multivariate adjusted logistics regression models." (PMID 37161054, 2023). "On the contrary, there was no significant influence of either gender or body composition indicator assessed such as body mass index and percentage of body fat (Pfor trend > 0.05) on the risk of sarcopenia after taking into account other factors such as age and blood IL-6 concentration." (PMID 37161054, 2023). "Furthermore, diet and nutrition play an important role in the onset of sarcopenia; for example, saturated fat can activate the innate immune system, leading to pro-inflammatory molecule production (IL6 and TNF-α), which, over time, causes insulin resistance." (PMID 35954203, 2022). "Similarly, IL‐1β and TNF‐α were positively associated (P < 0.05) with the presence of sarcopenia, while a trend existed for both IL‐6 (P = 0.06) and IL‐8 (P = 0.09)." (PMID 35080147, 2022). "IL-6 levels are associated with anorexia and high levels of other cytokines are related to increased lipolysis and muscle degradation contributing to the development of sarcopenia." (PMID 34383112, 2022). "Under Poisson Multivariate Model, PhA [Relative precision (RP): 0.364, Confidence Interval (CI) (95%):0.259–0.511, p < 0.001], Interleukin six (IL-6) [RP: 1.006, CI (95%):1.001–1.01, p = 0.02] and serum creatinine levels [RP: 0.788, CI (95%): 0.641–0.969, p = 0.024] were associated with sarcopenia." (PMID 35463026, 2022). "Chronically increased IL-6 levels have been linked to mitochondrial dysfunction, and sarcopenia." (PMID 34707570, 2021).
sarcopenia (continued). "Increased levels of TNF-alpha, IL-1, and IL-6 activate the ubiquitin-proteasome proteolytic pathway and play important roles in low-grade systemic inflammation; moreover, they have been implicated in the development of sarcopenia." (PMID 33997015, 2021). "In line, we found a significant positive correlation between the pre-interventional PMI and IL-10 serum levels as an example of an anti-inflammatory cytokine and a trend towards a positive correlation between the PMI and IL-6, supporting the association between systemic inflammation and sarcopenia." (PMID 31597337, 2019). "To investigate this question, we measured serum concentrations of the inflammatory cytokine IL-6 and the anti-inflammatory cytokine IL-10, and estimated the association between IL-6 levels, IL-10 levels, and IL-6/IL-10 ratios with sarcopenia in elderly individuals." (PMID 30541467, 2018). "Previous studies implicated IL-6 in mediating a proinflammatory response in patients with cancer cachexia, in women with anorexia nervosa and also in association with aging, sarcopenia, and muscle degeneration." (PMID 28545403, 2017). "On the other hand, the higher resting trough IL-6 levels that are associated with chronic and acute pro-inflammatory states and trauma appear to increase the risk of delirium and probably predispose to sarcopenia." (PMID 31011016, 2017). "Our objective was to study whether leptin, interleukin 6 (IL-6), and soluble urokinase plasminogen activator receptor (suPAR) were associated distinctively with adiposity, lipodystrophy and sarcopenia, in HIV-infected patients and healthy Controls." (PMID 26244048, 2015). "We therefore studied leptin, IL-6 and suPAR that we hypothesised would be associated distinctively with lipodystrophy, adiposity and sarcopenia." (PMID 26244048, 2015). "Thus we found leptin, IL-6 and suPAR to be associated with lipodystrophy, adiposity and sarcopenia distinctively." (PMID 26244048, 2015). "Our aim was therefore to study whether leptin, interleukin 6 (IL-6), and soluble urokinase plasminogen activator receptor (suPAR) were associated distinctively with adiposity, lipodystrophy and sarcopenia, in HIV-infected patients and healthy Controls." (PMID 26244048, 2015). "The analysis of classifier accuracy for E-DII + cfDNA showed its higher diagnostic utility in predicting sarcopenia then conventional inflammatory markers such as IL-1β, IL-6 and TNFα, which may have important implications in defining healthy or unhealthy ageing." (PMID 41345186, 2025). "This indicates that IL‐6 secreted by adipose tissue may cause sarcopenia." (PMID 39764565, 2025). "Pro-inflammatory cytokines (e.g., interleukin-6, and tumor necrosis factor-α) may trigger nociceptors, increase pain sensitivity, and lower pain threshold, while also causing muscle catabolism, resulting in sarcopenia in older adults." (PMID 41024053, 2025). "The analysis of E-DII with cfDNA (Classifier Accuracy 79.7%, p = 0.001) showed a higher diagnostic utility in sarcopenia prediction then conventional inflammatory markers such as IL-1β, IL-6 and TNFα, which may have important implications in defining healthy or unhealthy ageing." (PMID 41345186, 2025). "Whether the slow and sustained increase of IL-6 in the blood of elderly patients with sarcopenia causes damage to muscle fibers by influencing myofiber type transition and energy supply processes, thereby leading to atrophy of the whole skeletal muscle, still needs to be further explored." (PMID 40801027, 2025). "Chronic inflammation associated with sarcopenia and sarcopenic obesity as well as aging (the latter commonly referred to as inflammation) converges in altering the immune profile of muscle components with a tendency to release pro-inflammatory mediators such as IL-6." (PMID 39683624, 2024). "However, the presence of a causal relationship between IL-6, its receptor (IL-6R), and sarcopenia remains unclear." (PMID 38750566, 2024).
sarcopenia (continued). "Interestingly, only participants aged 70 years and above had an increased risk nine-fold risk of developing sarcopenia than their younger counterparts, after taking into account other potential confounding factors such as gender, and adiposity and blood IL-6 status." (PMID 37161054, 2023). "In addition, sarcopenia leads to mitochondrial DNA (mtDNA) mutations, increased release of reactive oxygen species (ROS), increased pro-inflammatory agents such as interleukin-6 (IL-6), and tumor necrosis factor-α (TNF-α), interleukin-1 (IL-1), as well as C-reactive protein (CRP)." (PMID 35250869, 2022). "In addition to treatment related factors, inactivity and malnutrition, sarcopenia among cancer survivors could also be attributed to loss of α-motoneuron, increased interleukin-6 (IL-6) and blunted secretion of growth hormone." (PMID 35159052, 2022). "Recent studies show that sarcopenia is associated with low-grade systemic inflammation, as indicated by increased inflammatory cytokines (IL-1, IL-6, and TNFα) leading to oxidative stress, which together with mitochondrial dysfunction, could be central to the pathogenesis of sarcopenia." (PMID 31888500, 2019). "Chronic systemic inflammation (e.g., IL-6, TNF-α–driven pathways) promotes proteolysis and metabolic derangements, and sarcopenia has been linked to dysregulated immune cell function and reduced antitumor immunity." (PMID 41597384, 2026). "The patient group with both high serum IL‐6 and sarcopenia had unfavourable tumour stages and surgical margins, as well as shorter OS and CSS, as compared with other groups (all p < 0.01)." (PMID 41380167, 2025). "Another study showed that higher levels of IL‐6 and IL‐8 are a prominent pathological feature of sarcopenia in elderly people." (PMID 39764565, 2025). "It is known that IL‐6 accelerates muscle wasting, exacerbating sarcopenia and creating a vicious cycle that further compromises patient recovery and survival." (PMID 41380167, 2025). "Elevated amounts of pro-inflammatory cytokines like interleukin-6 (IL-6) and tumor necrosis factor-α (TNF-α), as well as C-reactive protein (CRP), are linked to sarcopenia." (PMID 40649397, 2025). "The potential role of IL‐6 in sarcopenia is complex, as it has dual roles in muscle physiology and pathology." (PMID 39764565, 2025). "Both high IL‐6 and GDF‐15 in serum, as well as sarcopenia, are independent and combined risk factors in patients undergoing RC for BC." (PMID 41380167, 2025). "Inflammatory biomarkers play a pivotal role in the pathophysiology of sarcopenia and BC progression, with interleukin‐6 (IL‐6) being a key contributor." (PMID 41380167, 2025). "IL-6 plays a dual role in sarcopenia, depending on its expression level, duration, and physiological context." (PMID 41140691, 2025). "Studies have shown that sarcopenia patients often present with elevated levels of inflammatory mediators, including IL-6, TNF-α, and CRP32." (PMID 40664812, 2025). "The increased expression levels of IL-6 are positively correlated with the occurrence of sarcopenia, as well as TNF-α." (PMID 40265008, 2025). "This process is marked by the upregulation of inflammatory biomarkers such as C-reactive protein (CRP), IL-6, and TNF-α, all of which are associated with the development of sarcopenia." (PMID 39940321, 2025). "In multivariate analysis, a trend was shown for high IL‐6 to be an independent predictor of sarcopenia (p = 0.08)." (PMID 41380167, 2025). "Systemic inflammation—driven by cytokines such as TNF-α, IL-1β, and IL-6—is known to promote muscle catabolism and intramuscular lipid accumulation, thereby contributing to both sarcopenia and myosteatosis." (PMID 41567660, 2025). "Patients with both sarcopenia and high IL‐6 or GDF‐15 levels exhibited significantly worse overall survival and cancer‐specific survival in multivariate Cox regression analysis." (PMID 41380167, 2025).